EZR (ezrin)
Diseases named in the same sentence as EZR in open-access papers (continued):
Sharing a sentence is not in itself a finding about the gene and the disease.
osteosarcoma (continued). "Similarly, in osteosarcoma, multiple studies have suggested that ezrin expression is correlated with an increased risk for recurrence and worse overall survival." (PMID 28246524, 2017). "Increased ezrin expression has been associated with a poor prognosis in a variety of human cancers including osteosarcoma, soft tissue sarcomas (STS), breast, gastrointestinal, genitourinary, melanoma, astrocytoma, and squamous cell carcinoma of the head and neck." (PMID 28246524, 2017). "In this study, we sought to conduct a systematic review and meta-analysis to estimate whether ezrin immunoexpression was associated with outcome of osteosarcoma patient." (PMID 23805177, 2013). "Furthermore, high-level ezrin expression in canine osteosarcomas has been associated with early development of metastasis." (PMID 20569470, 2010). "Besides, it could also be possible that PARP1-Ezrin axis is relatively more dominant in osteosarcoma compared to other signaling pathways associated with cell migration and metastasis." (PMID 35173550, 2022). "A meta-analysis showed that elevated ezrin expression is associated with worse prognosis in patients with different cancer types (e.g., digestive cancers, head and neck squamous cell carcinoma, gynecological cancers, osteosarcoma, hepatobiliary cancer, and non-small cell lung cancer)." (PMID 34771571, 2021). "In addition, some meta-analysis results indicated that EZRIN positive immunoexpression could confer worse survival as well as a higher risk of recurrence in osteosarcoma patients." (PMID 31333725, 2019). "Phosphorylation of Thr235 works with phosphorylation of Thr576 for the full activation of ezrin, which is involved in the induction of osteosarcoma cell morphology changes during senescence." (PMID 39457653, 2024). "When PRL3 (phosphatase of regenerating liver 3) dephosphorylates Ezrin at Thr567, this can initiate protrusion formation, inducing lamellipodia formation in osteosarcoma U2OS cells." (PMID 37371090, 2023). "NSC305787 and NSC668394 are small-molecule inhibitors that directly bind to Ezrin to prevent phosphorylation at Thr567, and therefore interactions between Ezrin and actin, and were found to inhibit osteosarcoma cell Ezrin-mediated motility." (PMID 37371090, 2023). "Among 16 identified proteins, alpha-crystallin B chain (CRYAB) and ezrin (EZR1) were further validated using immunohistochemistry of tissue microarrays of paired osteosarcoma and normal tissues." (PMID 36077137, 2022). "Another study found that G1749-A1771 siRNA targeting ezrin mRNA effectively downregulated the expression of ezrin, contributing to the induction of apoptosis and the inhibition of cell proliferation in osteosarcoma cells." (PMID 36355541, 2022). "We discovered that PARP1 interacted with a protein playing a crucial role in osteosarcoma metastasis - ezrin and regulated its phosphorylation." (PMID 35173550, 2022). "The overexpression of vimentin and ezrin genes was associated with epithelial-mesenchymal transition (EMT), a key process in metastasis and progression in osteosarcoma (OS)." (PMID 35625426, 2022). "Bulut and colleagues previously demonstrated the efficacy of blocking ezrin function using small-molecule inhibitors in preclinical osteosarcoma models of metastasis." (PMID 36923551, 2022). "Further along this line, siRNA‐mediated downregulation of ezrin inhibits osteosarcoma cell proliferation, while ezrin overexpression induces proliferation in this tumor entity." (PMID 34228897, 2022). "The multi-kinase inhibitor sorafenib (BAY43-9006) promoted apoptosis by inhibiting the ezrin pathway and inhibited angiogenesis and metastasis in a mouse model of osteosarcoma." (PMID 36355541, 2022).
osteosarcoma (continued). "EZRIN expression provides an early survival advantage for cancer cells and plays an important role in the invasion of other tissues in pediatric osteosarcoma." (PMID 34071614, 2021). "Consistent with findings in osteosarcoma, Ezrin was found to be highly expressed in pancreatic cancer tissues and to positively regulate cell proliferation and invasion through the activation of the Akt/mTOR pathway." (PMID 33240887, 2020). "EZRIN has been described as a metastatic determinant in many different tumor types, including mesenchymal tumors such as osteosarcoma." (PMID 32664538, 2020). "These authors demonstrated a reduction in the invasive phenotype of cancer cells and inhibition of lung metastases in mice treated with ezrin inhibitors in osteosarcoma experimental models." (PMID 30678714, 2019). "Despite other ERM proteins, ezrin knock down in osteosarcoma cells of both human and mouse models resulted in inhibition of metastasis." (PMID 30996241, 2019). "In the present study, we mainly validated EZRIN as the direct target gene of miR211 in human osteosarcoma cells." (PMID 31333725, 2019). "miR211 transfection also decreased the EdU staining and the number of colonies in normal osteosarcoma cells, and EZRIN overexpressed 143B cells, which was consistent with the CCK-8 results." (PMID 31333725, 2019). "We found that both the mRNA and the protein level of EZRIN were inhibited by the up-regulation of miR211 in human osteosarcoma cells (P<0.05)." (PMID 31333725, 2019). "We found that both miR211 overexpression and EZRIN siRNA transfection increased the percentage of G0/G1 phase and decreased the percentage of S phase in the human osteosarcoma cells." (PMID 31333725, 2019). "In the present study, we mainly demonstrated that miR211 targeted the 3′-UTR of EZRIN, and regulated the expression of EZRIN negatively in both human osteosarcoma tissues and cells." (PMID 31333725, 2019). "miR211 overexpression increased the level of apoptosis in a human osteosarcoma cell line and inhibited cell proliferation ability as well as cell migration/invasion ability in 143B cells via suppressing the expression of EZRIN." (PMID 31333725, 2019). "The expression levels of miR211 and EZRIN were measured in both human osteosarcoma cells and tissues." (PMID 31333725, 2019). "In conclusion, we mainly found that EZRIN can be targeted by miR211 in human osteosarcoma, and miR211 regulated the expression of EZRIN negatively." (PMID 31333725, 2019). "Our previous study had indicated that miR96 acts as a tumor suppressor gene in human osteosarcoma via target regulation of EZRIN." (PMID 31333725, 2019). "Our study demonstrates that adenovirus-mediated siRNA targetting ezrin can induce apoptosis and inhibit the proliferation, migration, and invasion of human osteosarcoma MG-63 cells." (PMID 29899165, 2018). "Recently, small molecules that are able to prevent the metastasis of osteosarcoma cells by targetting ezrin is discovered, making it requisite to explore the predictive role of ezrin in osteosarcoma." (PMID 29899165, 2018). "The correlations between ezrin expression and malignant tumors have been revealed amongst multiple human cancers, including prostate cancer, colorectal cancer, and osteosarcoma." (PMID 29899165, 2018). "The present study aims to investigate the effect of recombinant adenovirus mediated si-ezrin on the proliferation, migration, invasion, and apoptosis of human osteosarcoma MG-63 cells." (PMID 29899165, 2018). "Initially, our study found that adenovirus-mediated siRNA targetting ezrin can mediate the mRNA and protein expressions of ezrin in human osteosarcoma MG-63 cells." (PMID 29899165, 2018).
osteosarcoma (continued). "The present study attempts to explore the effect of adenovirus-mediated siRNA targetting ezrin on the proliferation, migration, invasion, and apoptosis of human osteosarcoma MG-63 cells." (PMID 29899165, 2018). "Previous studies have confirmed that NSC668394 blocks ezrin C-terminal threonine phosphorylation, ezrin–actin interaction and ezrin-dependent motility of osteosarcoma cells in culture." (PMID 29777033, 2018). "All results indicated that si-ezrin inhibit the invasion and migration of human osteosarcoma MG-63 cells." (PMID 29899165, 2018). "Suppression of ezrin expression and disruption of its significantly reduced lung metastasis in a mouse osteosarcoma model." (PMID 29291001, 2017). "A meta-analysis was conducted to evaluate the expression level of ezrin in osteosarcoma patients compared to patient prognosis." (PMID 28061797, 2017). "For example, in patients with osteosarcoma, ezrin protein expression level in vivo is higher than normal." (PMID 28355349, 2017). "Compounds that are able to successfully inhibit ezrin are being researched to serve as potential therapeutics for osteosarcoma." (PMID 28061797, 2017). "Another work from the same group demonstrated that in osteosarcoma cells activation and inactivation of ezrin are essential for tumor growth and migration." (PMID 29209287, 2017). "For patients with high-grade STS and osteosarcoma, high ezrin expression has been correlated with inferior EFS and OS and with an increased incidence of metastasis for patients with STS." (PMID 28246524, 2017). "In F5M2cells, miR-183 inhibits the metastasis of osteosarcoma, the most common primary malignancy of bones, and influences the migration and invasion of osteosarcomas by targeting Ezrin." (PMID 28570710, 2017). "Similar behavior was described in osteosarcoma cells in which binding to F-actin by C-terminal inactive ezrin occurs similarly to the wild type ezrin." (PMID 29209287, 2017). "While the expression of ezrin protein is decreased by siRNA, the proliferation, invasion and migration of osteosarcoma cells were significantly inhibited, which is indicative of the essential function of ezrin overexpression in those processes." (PMID 28355349, 2017). "High expression of ezrin protein correlates with the metastatic potential of several cancers, including prostatic intraepithelial neoplasia, osteosarcoma, rhabdomyosarcoma, and CRC." (PMID 29291001, 2017). "Studies have shown that the invasion of ezrin protein is related to metastasis of tumor cells, such as from osteosarcoma and lung cancer, and is considered a key regulator of metastasis." (PMID 28355349, 2017). "Notable, expression of Ezrin at high levels has been found in metastatic human and canine osteosarcoma and functionally validated in model systems as a driver of osteosarcoma metastasis." (PMID 29056713, 2016). "Increasing evidences indicated that ezrin is involved in osteosarcoma progression and metastasis and that the levels of PIP2 play a critical role for its activation." (PMID 27026853, 2016). "Phosphatydil inositol bisphosphate (PIP2), belonging to the Phosphoinositide (PI) signal transduction pathway, was related to the regulation of ezrin, an ezrin–radixin–moesin protein involved in metastatic osteosarcoma spread." (PMID 27026853, 2016). "It has been confirmed that Ezrin is overexpressed and involved various aspects of cancer cell biological behaviors, such as invasion and metastasis in breast cancer, osteosarcoma, and rhabdomyosarcoma." (PMID 25126570, 2014). "A pool of studies published between 2007 and 2010 on the association between ezrin immunoexpression and patient's survival, serum alkaline phosphatase (ALP) level, histological response to adjuvant chemotherapy and recurrence in osteosarcoma were analyzed." (PMID 23805177, 2013). "The cytoskeletal organizer, ezrin, was first identified as an important metastatic regulator in rhabdomyosarcoma and osteosarcoma." (PMID 24182314, 2013).
osteosarcoma (continued). "The aim was to provide a meta-analysis for ezrin immunoexpression and prognostic features of osteosarcoma patients." (PMID 23805177, 2013). "Three studies with a total of 202 osteosarcoma patients dealing with ezrin immunoexpression and EFS were meta-analyzed." (PMID 23805177, 2013). "Recently, the discovery of small molecules that prevent osteosarcoma cells metastasis by directly targeting ezrin made it necessary to analyze the predictive value of ezrin in osteosarcoma with lines of published clinical investigations." (PMID 23805177, 2013). "Further studies are required to fully understand the regulation mechanisms of miR-183 and Ezrin in osteosarcoma in vitro and in vivo." (PMID 22922800, 2012). "In our study, ectopic overexpression of miR-183 repressed the expression levels of Ezrin and significantly inhibited the motility and invasion of osteosarcoma cells." (PMID 22922800, 2012). "In osteosarcoma studies, EZR was necessary for metastasis, and a high expression of ezrin was associated with the early development of metastasis." (PMID 23226966, 2012). "The findings of this study illustrate that by downregulating the Ezrin expression level, miR-183 plays a suppressing role in cell migration and invasion of osteosarcoma." (PMID 22922800, 2012). "Our findings also demonstrated that Ezrin levels were positively correlated with osteosarcoma invasion and metastasis." (PMID 22922800, 2012). "Known genes involved in bone metabolism and osteosarcoma were identified as highly expressed, and the putative new marker Ezrin was also identified." (PMID 14676807, 2003). "The interplay linking PI-PLC inhibition and osteosarcoma suppression could occur through regulating ezrin, a protein belonging to the ezrin–radixin–moesin (ERM) family." (PMID 40572742, 2025). "Protein kinase C (PKC) phosphorylates ezrin to regulate osteosarcoma cell migration." (PMID 39457653, 2024). "It was proposed that the evaluation of biomarkers characteristic for osteosarcoma cells such as VIM, Ezrin and COL5A2 in blood may be used as a diagnostic and prognostic tool for patients with osteosarcoma." (PMID 37511619, 2023). "As one type of sarcoma, osteosarcoma shares similar characterizations and it could be possible that PARPi induced ezrin phosphorylation and OS metastasis discovered in this study is related with the failure of these clinical trials." (PMID 35173550, 2022). "Ezrin can be a valuable biomarker for prognosis and therapeutic target in osteosarcoma." (PMID 36077137, 2022). "The mechanism of ezrin-mediated metastasis in osteosarcoma involves kinase pathways." (PMID 36077137, 2022). "Furthermore, the natural compound, Baicalein, effectively suppresses the invasion and migration of osteosarcoma cell lines through upregulation of miR-183 and downregulates the mRNA and protein level of ezrin." (PMID 36077137, 2022). "Similarly, phosphorylated ezrin was found at the invasive front of large metastatic lesions in osteosarcoma." (PMID 31936668, 2020). "For example, in osteosarcoma, Ezrin allows metastatic tumor cells to overcome a number of stresses as cells from the primary lesion are able to break loose and effectively initiate the growth of secondary lesions by generating additional ATP from a variety of sources." (PMID 33240887, 2020). "Dysregulation of miR-183 through Ezrin targeting promotes osteosarcoma tumor metastasis." (PMID 33240887, 2020).
osteosarcoma (continued). "As most of the extracted data were obtained from patients with osteosarcoma, and in order to evaluate if the prognostic value of ezrin expression was limited to osteosarcoma, in the analysis of OS and EFS, a subgroup analysis according to tumor type (osteosarcoma vs. nonosteosarcoma) was performed." (PMID 31376222, 2019). "Furthermore, Ezrin has been reported to be a molecule that is involved in the invasion of osteosarcoma cells." (PMID 31003401, 2019). "In addition, a human osteosarcoma cell line, 143B, was used to analyze the negative regulatory relationship between miR211 and EZRIN in osteosarcoma." (PMID 31333725, 2019). "In addition, the overexpression of miR211 suppressed osteosarcoma cell proliferation ability obviously and also inhibited the promoting effect of EZRIN overexpression." (PMID 31333725, 2019). "In addition, miR211 overexpression can also inhibit the influence of EZRIN overexpression on both migration and invasion ability of 143B cells, suggesting the key position of miR211 in migration/invasion of human osteosarcoma cells (P<0.05)." (PMID 31333725, 2019). "In this study, the relationship between miR211 and EZRIN was analyzed in human osteosarcoma." (PMID 31333725, 2019). "The CCK-8 results showed that osteosarcoma cell proliferation ability was inhibited by the EZRIN siRNA, while the proliferation index could be enhanced via EZRIN overexpression." (PMID 31333725, 2019). "Therefore, the increased expression levels of MMPs and Ezrin due to the aberrant expression of miRNA promote the migration and invasion of osteosarcoma cells and are thus involved in osteosarcoma progression." (PMID 31003401, 2019). "The results showed that ezrin overexpression could predict poor OS in both osteosarcoma (HR 3.15, 95% CI: 2.39–4.14, P < 0.01, PFDR < 0.01) and nonosteosarcoma (HR 2.38, 95% CI: 1.24–4.58, P = 0.01, PFDR = 0.01)." (PMID 31376222, 2019). "We hypothesized that adenovirus-mediated siRNA targetting ezrin may inhibit the proliferation, metastasis, and invasion and promote apoptosis of osteosarcoma MG-63 cells, with hope to be helpful for future treatment of osteosarcoma." (PMID 29899165, 2018). "As one widely studied cytoskeleton linker protein, ezrin was found widely expressed in the cytoplasm, and previous study also demonstrated that the ezrin expression was related with the growth, metastasis, and poor prognosis in osteosarcoma." (PMID 29899165, 2018). "Furthermore, adenovirus-mediated siRNA targetting ezrin inhibited human osteosarcoma MG-63 cell viability, growth, invasion, and migration, and promoted apoptosis." (PMID 29899165, 2018). "A previous study reported that mRNA expression of ezrin may serve as a predictor and a prognostic factor of potential metastasis in lung amongst Chinese osteosarcoma patients." (PMID 29899165, 2018). "The objective of the present study, therefore, is to determine whether the carrier for recombinant adenovirus targetted ezrin affects the cell viability of human osteosarcoma MG-63 cells." (PMID 29899165, 2018). "The prognostic value of Ezrin has been reported in osteosarcoma." (PMID 29190988, 2017). "In addition, miR-150 overexpression inhibited invasion and metastasis of osteosarcoma cells, which was achieved by decreasing Ezrin expression." (PMID 29069797, 2017). "Moreover, the overexpression of Ezrin often correlates with poor prognosis of patients in cervical cancer, osteosarcoma, colorectal adenocarcinoma, and gastrointestinal cancers." (PMID 25126570, 2014). "We previously reported that mRNA level of ezrin could be a prognostic factor and a predictor of potential lung metastasis in Chinese osteosarcoma patients." (PMID 23805177, 2013). "However, the prognostic value of ezrin expression in osteosarcoma patient's survival or other clinical features, such as recurrence and histological response to adjuvant chemotherapy, remains controversial." (PMID 23805177, 2013).